AIM2 (absent in melanoma 2)
Description:
Sensor component of the AIM2 inflammasome, which mediates inflammasome activation in response to the presence of double-stranded DNA (dsDNA) in the cytosol, leading to subsequent pyroptosis. Inflammasomes are supramolecular complexes that assemble in the cytosol in response to pathogens and other damage-associated signals and play critical roles in innate immunity and inflammation. Acts as a recognition receptor (PRR): specifically recognizes and binds dsDNA in the cytosol, and mediates the formation of the inflammasome polymeric complex composed of AIM2, CASP1 and PYCARD/ASC. Recruitment of pro-caspase-1 (proCASP1) to the AIM2 inflammasome promotes caspase-1 (CASP1) activation, which subsequently cleaves and activates inflammatory cytokines IL1B and IL18 and gasdermin-D (GSDMD), promoting cytokine secretion. In some cells, CASP1 activation mediates cleavage and activation of GSDMD, triggering pyroptosis without promoting cytokine secretion. Detects cytosolic dsDNA of viral and bacterial origin in a non-sequence-specific manner. Involved in the DNA damage response caused by acute ionizing radiation by mediating pyroptosis of intestinal epithelial cells and bone marrow cells in response to double-strand DNA breaks (By similarity). Mechanistically, AIM2 senses DNA damage in the nucleus to mediate inflammasome assembly and inflammatory cell death (By similarity). Also acts as a regulator of neurodevelopment via its role in the DNA damage response: acts by promoting neural cell death in response to DNA damage in the developing brain, thereby purging genetically compromised cells of the central nervous system (By similarity). Pyroptosis mediated by the AIM2 inflammasome in response to DNA damage is dependent on GSDMD without involving IL1B and IL18 cytokine secretion (By similarity). Also acts as a mediator of pyroptosis, necroptosis and apoptosis (PANoptosis), an integral part of host defense against pathogens, in response to bacterial infection (By similarity). Can also trigger PYCARD/ASC-dependent, caspase-1-independent cell death that involves caspase-8 (CASP8) (By similarity). Also acts as a tumor suppressor independently of its role in inflammatory response. Able to suppress overt cell proliferation in enterocytes: restricts stem cell proliferation in the intestinal mucosa in an inflammasome-independent manner, contributing to a decrease in the likelihood of colorectal cancer development (By similarity). AIM2 suppresses cell proliferation by inhibiting phosphorylation of AKT1 at 'Ser-473', preventing AKT1 activation and AKT-mTOR signaling pathway (By similarity). Inhibits AKT1 phosphorylation both by inhibiting the activity of PRKDC/DNA-PK kinase and promoting dephosphorylation by PP2A phosphatase (By similarity). Also acts as a key regulator of regulatory T-cells (Treg) homeostasis by promoting their stability: acts by preventing AKT1 activation (By similarity). Its role in Treg homeostasis is important to restain autoimmune diseases (By similarity).
Synonyms: PYHIN4
Tractability: PROTAC: ubiquitination databases record sites on it.
Gene: Protein-coding gene on chromosome 1 (159,056,129 to 159,188,222, reverse strand). Ensembl gene ENSG00000163568.
Subcellular location: Cytoplasm; Inflammasome; Nucleus
Subcellular location (Human Protein Atlas): Mitochondria; Cytosol; Nucleoplasm
Pathways (Reactome):
Immune System: Cytosolic sensors of pathogen-associated DNA; The AIM2 inflammasome
Gene Ontology:
Molecular function: cysteine-type endopeptidase activator activity; double-stranded DNA binding; identical protein binding; pattern recognition receptor activity; protein binding; signaling adaptor activity
Biological process: activation of innate immune response; AIM2 inflammasome complex assembly; cellular response to xenobiotic stimulus; positive regulation of interleukin-1 beta production; pyroptosome complex assembly; pyroptotic inflammatory response; tumor necrosis factor-mediated signaling pathway; brain development; cellular response to interferon-beta; defense response to virus; DNA damage response; immune response; negative regulation of phosphatidylinositol 3-kinase/protein kinase B signal transduction; neuron cellular homeostasis; pattern recognition receptor signaling pathway; positive regulation of defense response to virus by host; positive regulation of inflammatory response; regulation of behavior; T cell homeostasis; cellular response to cytokine stimulus
Cellular component: AIM2 inflammasome complex; canonical inflammasome complex; cytoplasm; cytosol; mitochondrion; nucleoplasm; nucleus; site of double-strand break
Genetic constraint (gnomAD): Loss-of-function variants: 31 observed, 29.44 expected, observed/expected ratio (o/e) 1.05, 90% interval 0.79 to 1.42. The upper end of that interval is the gene's LOEUF score, 1.42, which puts it in group 5 of 6, group 1 being the genes least tolerant of losing a copy. Missense variants: 358 observed, 432.53 expected, observed/expected ratio (o/e) 0.83, 90% interval 0.76 to 0.9. Synonymous variants: 141 observed, 153.29 expected, observed/expected ratio (o/e) 0.92, 90% interval 0.8 to 1.06.
Homologues: Orthologues: chimpanzee AIM2 (98% identical), macaque AIM2 (91% identical), rat Aim2 (57% identical), mouse Aim2 (56% identical). Paralogues in human: MNDA (37% identical), IFI16 (36% identical), PYHIN1 (36% identical).
Diseases named in the same sentence as AIM2 in open-access papers:
AIM2 is named in the same sentence as 324 diseases in open-access papers, as found by Europe PMC text mining. Sharing a sentence is not in itself a finding about the gene and the disease. The quoted sentences say what the papers report.
melanoma (107 papers, 2010 to 2026). A malignant, usually aggressive tumor composed of atypical, neoplastic melanocytes. "Early research has demonstrated that AIM2 overexpression is able to delay proliferation, increase cell death susceptibility, and reverse the melanoma phenotype." (PMID 40002808, 2025). "Tumor-infiltrated dendritic cells (TIDCs) highly expressed AIM2 and its levels were associated with tumor progression in human melanoma patients." (PMID 40002808, 2025). "The gene encoding AIM2 was originally isolated from human melanoma cells and identified as a gene in which expression was lost in these cells." (PMID 40002808, 2025). "Although AIM2 has beneficial roles in promoting host defense responses, inappropriate activation of AIM2 is associated with worsening of diseases such as atherosclerosis, cancers such as melanoma, ischemic stroke, and post-stroke immunosuppression." (PMID 37216118, 2023). "AIM2 was originally discovered to be a tumor suppressor gene in human melanomas, and reduced AIM2 expression was associated with poor prognosis in patients and AIM2 mutations in human colorectal tumors." (PMID 34697412, 2022). "Additionally, AIM2-deficient DCs enhance the infiltration of tumor antigen-specific CD8+ T cells into melanoma tumors via CXCL10." (PMID 41291696, 2025). "AIM2 mutations have been found in 56% of small bowel cancers but in only 2% of melanomas." (PMID 36742336, 2023). "Research has shown that overexpression of AIM2 can potentially reverse the malignant characteristics of melanoma cells." (PMID 39744568, 2025). "In the following subparagraphs, we summarize the studies that demonstrated that AIM2 has an anti-tumor function in colon, colorectal and breast cancer, melanoma, hepatocellular carcinoma, bladder cancer, osteosarcoma, and brain tumors." (PMID 40002808, 2025). "Research indicates that AIM2 expression in human melanoma DCs is correlated with poor prognosis and exhibits immunosuppressive properties." (PMID 39744568, 2025). "Due to the discrepancies, it is clear that the role of AIM2 in melanoma requires further investigation." (PMID 40002808, 2025). "Initially, AIM2 was identified as a tumor suppressor in melanoma and colorectal cancer, but other studies on tumor-derived DNA, have demonstrated the pro-tumor activity of AIM2, as also demonstrated by our laboratory." (PMID 40002808, 2025). "Focusing on the DC compartment, it is well known that the recruitment of AIM2-expressing pDCs and resting DCs in NSCLC is associated with the establishment of immunosuppressive TME, as also observed in melanoma." (PMID 40002808, 2025). "Later, it was found that AIM2 was upregulated in acute and chronic inflammatory skin conditions, in melanocytic nevi and in most primary melanomas." (PMID 40002808, 2025). "AIM2 PANoptosome also acts as a tumor suppressor by eliminating transformed cells through PANoptosis in colorectal cancer, and the downregulation of AIM2 led to accelerated proliferation of melanoma cells." (PMID 40721869, 2025). "Although AIM2 was first identified as a tumor suppressor in melanoma, most research on AIM2 has focused on its role in inflammasome activation and innate immune response against intracellular pathogens." (PMID 38429284, 2024). "AIM2 is minimally expressed in melanoma and was originally identified as a tumor suppressor gene, exerting anti-tumor effects through both inflammasome-dependent and independent signaling pathways in tumors." (PMID 39600708, 2024). "Apart from cGAS/STING activation, toll-like receptor 9 (TLR9) and absence in melanoma 2 (AIM2) initiate responses to cytosolic DNA." (PMID 38990864, 2024). "By analyzing gene expression profiles of normal skin and melanoma cells, Li and colleagues reported a set of 5 key prognostic, differentially expressed PYR-associated genes (GSDM A, GSDM C, IL18, NLRP6 and AIM2)." (PMID 36674798, 2023).
melanoma (continued). "Through our analysis of a mouse model of cold melanoma and melanoma specimens from patients, we revealed that AIM2 exerts an immunosuppressive effect within the melanoma microenvironment in mice and correlates with tumor progression in human melanoma patients." (PMID 37046775, 2023). "IL-18 is also known to play a key role in melanoma regulation and is one of the AIM2 inflammasome components, recently recognized as a potential target for melanoma treatment." (PMID 35205739, 2022). "The authors examined the expression of AIM2 in DC and found that tumor-infiltrating DC with AIM2-expression in human melanoma were increased and correlated with tumor progression." (PMID 35739593, 2022). "AIM2 was initially demonstrated as a tumor‐suppressive factor in the control of tumorigenicity in melanoma." (PMID 34014039, 2021). "T cell reactivity against AIM2 has been found in patients with melanoma, suggesting that AIM2‐derived peptides are an ideal candidate for immunomonitoring." (PMID 34014039, 2021). "Further studies showed that the expression of AIM2 was related to the inhibition of melanoma phenotype." (PMID 34014039, 2021). "With respect to its tumor-modulating effects, AIM2 was initially identified as a melanoma tumor suppressor gene, which the present study confirmed." (PMID 34721986, 2021). "Absent in melanoma 2 (AIM2) was initially identified in melanoma, in which it showed decreased expression." (PMID 33828074, 2021). "The AIM2 sensor was discovered in experiments designed to suppress tumorigenicity of melanoma cells by transfer of chromosome 6 from normal cells." (PMID 32027447, 2020). "Immunohistochemistry studies have shown high levels of AIM2 in inflammatory skin disorders and in primary melanoma (de Koning, van Vlijmen‐Willems, Zeeuwen, Blokx, & Schalkwijk, 2014)." (PMID 32027447, 2020). "AIM2 was originally investigated in melanoma cells and its absence in melanoma tissues promoted disease progression." (PMID 27167192, 2016). "AIM2 was first reported in malignant melanoma cell lines and was thought to act as a tumor suppressor by repressing NF-κB transcriptional activity." (PMID 26290184, 2015). "AIM2 was first reported to act as a putative tumor suppressor in malignant melanoma, but the AIM2 inflammasome complex is more widely known as an essential mediator of host defense against cytosolic bacteria and DNA viruses." (PMID 24701032, 2014). "In contrast, AIM2 upregulation promoted cell growth, metastasis and immunosuppression through the inflammasome-dependent pathway and correlated with poor survival in non-small cell lung cancer, melanoma and triple-negative breast cancer." (PMID 38166970, 2024). "AIM2 impedes anti-tumor responses in melanoma by limiting immunogenic type I IFN responses." (PMID 37216118, 2023). "The functions of AIM2 have been investigated in many cancer types, including melanoma." (PMID 37046775, 2023). "AIM2 is hardly expressed in melanomas and was initially discovered as a tumor suppressor gene." (PMID 37046775, 2023). "AIM2 was originally discovered in melanoma, in which its expression level was decreased." (PMID 36276158, 2022). "AIM2 exerts an immunosuppressive effect within the melanoma microenvironment." (PMID 35281845, 2022). "Finally, AIM2 inflammasome is low expressed in Melanoma, Colon cancer, Hepatocellular carcinoma, Renal carcinoma, Breast cancer, Prostate cancer, playing a tumor suppressive role." (PMID 36248785, 2022). "In addition, T cell reactivity against AIM2 has also been found in melanoma, indicating that AIM2-derived peptides can serve as relevant targets for immunomonitoring." (PMID 35281845, 2022). "Thus, anti-PD-1 Ab in combination with Aim2-suppressed DC vaccine (intravenous or intra-tumoral injection) or Aim2 siRNA (intra-tumoral injection) will be a new treatment strategy for melanoma." (PMID 35432377, 2022). "AIM2 was first identified in melanoma and is an interferon-inducible protein." (PMID 36115937, 2022).
melanoma (continued). "Additionally, we found that DC expression of AIM2 within human melanoma correlates with poor prognosis, and AIM2 exerts an immunosuppressive effect within the melanoma." (PMID 35432377, 2022). "Early studies found that the overexpression of AIM2 could reverse the melanoma phenotype.Therefore, AIM2 has always been present as a tumor suppressor." (PMID 36248785, 2022). "AIM2 was originally described as a tumor suppressor for melanoma." (PMID 34014039, 2021). "In melanoma, AIM2 is initially identified as a tumor suppressor factor." (PMID 34014039, 2021). "AIM2 was first reported to act as a putative tumor suppressor in malignant melanoma." (PMID 24325587, 2013). "AIM2 or PYHIN4 was initially identified in a human malignant melanoma cell line, where the absence of AIM2 caused increased cell growth and has subsequently been mostly studied in the context of cancer." (PMID 24367371, 2013). "Hence, there is a low probability that drugs targeting AIM2 will act on melanoma cells." (PMID 37046775, 2023). "Intravenous administration of AIM2-deficient dendritic cells (DCs) using a vaccination strategy results in the homing of the DCs to the tumor and enhanced efficacy of adoptive cell therapy (ACT) as well as anti-PD-1 immunotherapy, thereby achieving therapeutic responses in cold melanomas." (PMID 37046775, 2023). "Specifically, related to the activation of the inflammasome, we can see changes in genes such as Nlrp3 (NLR family pyrin domain containing 3), Pycard (often referred to as ASC, apoptosis-associated speck-like protein containing a CARD), or Aim2 (absent in melanoma 2)." (PMID 34413771, 2021). "Similarly, AIM2 was identified as a gene whose expression was lost in a melanoma cell line." (PMID 33138274, 2020). "Therefore, we co-transfected THP-1 clones genetically deficient in cGAS, STING or Absent In Melanoma-2 (AIM2) with 3P-dsRNA:imDNA complexes." (PMID 27941826, 2016). "Within the immune system broadly, a large number of genes were identified with known roles in cancer, including AIM2, C1QA, and DFNA5 (also known as GSDME), which have been identified to have a mechanistic role in melanoma tumor growth." (PMID 35008167, 2021). "Although AIM2 is the best characterized member of the human PYHIN family, it was only the third to be discovered, initially as being suppressed in a malignant melanoma cell line." (PMID 33353088, 2020). "Absent in Melanoma 2 (AIM2) was first discovered as a gene that was not present in melanoma cell lines using subtractive cDNA hybridization." (PMID 40643515, 2025). "Absent in melanoma 2 (AIM2) was discovered in melanoma in 1997 and was initially characterized as a tumor suppressor gene." (PMID 39744568, 2025). "To explore the broader effects of MLT‐MLP on other inflammasome activation, we established in vitro cell models for the absent in melanoma 2 (AIM2) and NLR family CARD domain‐containing protein 4 (NLRC4) inflammasomes." (PMID 39717013, 2025). "In mammals, DNA recognition is carried out by Toll-like receptor (TLR9), cyclic GMP–AMP synthase, and “absent in melanoma 2” (AIM2), depending on its localization in either the endosomal compartment or the cytoplasm." (PMID 40407422, 2025). "Remarkably, one Saru LTR regulates innate immunity: it is an interferon-induced enhancer of AIM2 (Absent in Melanoma 2)." (PMID 40083010, 2025). "To date, four distinct PANoptosomes have been identified: Z-DNA-binding protein 1 (ZBP1), absent in melanoma 2 (AIM2), receptor-interacting protein kinase 1 (RIPK1), and nucleotide-binding leucine-rich repeat-containing receptor 12 (NLRP12) PANoptosomes." (PMID 40568592, 2025). "Absent in melanoma 2 (AIM2) serves as an intracellular nucleic acid sensor that predominantly detects double-stranded DNA (dsDNA) within the cells." (PMID 39600708, 2024). "The fundamental constituent of inflammasomes, comprising pyrin, the NOD-like receptor (NLR) family (NLRP1, NLRP3, NLRP6, NLRP9, and NLRC4), and absent in melanoma 2 (AIM2)." (PMID 39125817, 2024).